PTH (parathyroid hormone)
Diseases named in the same sentence as PTH in open-access papers (continued):
Sharing a sentence is not in itself a finding about the gene and the disease.
hypophosphatemia (continued). "All the adults were diagnosed based upon relevant clinical (bone pain, walking difficulty, muscle weakness) and laboratory findings (hypophosphatemia, mild-moderate elevated PTH, increased renal phosphate loss)." (PMID 29505567, 2018). "Excess FGF23 production in individuals with normal kidney function causes hypophosphatemia, low serum parathyroid hormone (PTH) levels, low plasma 1,25 dihydroxyvitamin D3 (1,25OHD) levels, and bone demineralization." (PMID 28475601, 2017). "Simultaneous increases in serum levels of inorganic phosphate and TmP/GFR after treatment start suggest that the correction of hypophosphatemia is caused by a positive balance of phosphate, likely mediated by a reduction in PTH-induced phosphaturia." (PMID 25861621, 2015). "Deletion of PTH in CaR−/− mice rescued the phenotype of cartilage associated with the up-regulation of PTHrP expression in chondrocytes and correction of hypophosphatemia." (PMID 21966280, 2011). "This is important because hypophosphatemia may be attributed to the influence of PTH and XLH overlooked as a diagnostic consideration." (PMID 41185884, 2025). "In our case, there was persistent hypophosphatemia along with normal values of serum calcium, serum magnesium, serum 25-hydroxy vitamin D, and parathyroid hormone levels, along with evidence of renal phosphate loss demonstrated by low %TRP of 83% and low TmP/GFR of 2.07 mg/dL." (PMID 39055417, 2024). "The biochemical hallmark of TIO includes renal phosphate wasting-induced hypophosphatemia, elevated levels of parathyroid hormone (PTH) and alkaline phosphatase (ALP), inappropriately normal or frankly low 1, 25-dihydroxyvitamin D, and inappropriately normal or elevated FGF23 levels." (PMID 38887276, 2024). "Increased PTH levels lead to loss of phosphate in the urine and, consequently, hypophosphatemia." (PMID 37630705, 2023). "In addition, PTH causes internalization, and subsequent degradation, of NaPi2a and NaPi2C in the proximal tubule, leading to renal phosphate wasting and consecutive hypophosphatemia." (PMID 34910242, 2022). "In particular, total calcium concentrations can appear spuriously lower and PTH can be physiologically suppressed; nevertheless, the combination of increased ionized or albumin-corrected calcium, and/or hypophosphatemia associated with detectable PTH is indicative of pHPT in most cases." (PMID 33925967, 2021). "Hypophosphatemic vitamin D resistant rickets is characterized by copious renal phosphate loss, resulting in elevated urine phosphorus, hypophosphatemia, normal serum levels of calcium, normal or slightly elevated serum PTH and normal or mildly depressed 1, 25-(OH)2D3." (PMID 33004071, 2020). "The main causal factors involved in the genesis of hypophosphatemia are: decreased activity of the sodium-phosphate co-transporter in the proximal tubule by PTH action, leading to phosphaturia; dysfunction of proximal tubule; excess of FGF23; renal denervation; and calcineurin inhibitor tubulopathy." (PMID 32720971, 2020). "The reduction in calcium levels could represent a stimulus for the increased PTH secretion by the parathyroid glands and, in turn, the secondary increase of PTH can mediate the increased phosphaturia and the alteration in phosphate reabsorption, which causes hypophosphatemia." (PMID 36672478, 2023). "However, emerging evidence from clinical trials has revealed that klotho therapies may disrupt Ca2+ homeostasis by controlling parathyroid hormone (PTH) secretion, and intravenous infusion of klotho may also cause hypophosphatemia and phosphaturia." (PMID 36120595, 2022). "Laboratory evaluation revealed marked hypophosphatemia, phosphaturia, and elevated alkaline phosphatase and parathyroid hormone levels." (PMID 41664797, 2026).
hypophosphatemia (continued). "Biochemical investigations revealed moderate renal impairment (eGFR 40 mL/min/1.73 m2), hypophosphatemia, metabolic alkalosis, hyperchloremia, and elevated parathyroid hormone, consistent with a proximal renal tubular acidosis (pRTA)." (PMID 41427162, 2025). "Biochemistry revealed mild hypophosphatemia (0.57 mmol/L [refence range 0.75-1.50 mmol/L]) with normal parathyroid hormone (5.3 pmol/L, [1.7-10.0 pmol/L]) and 1,25(OH)2D3." (PMID 41445556, 2025). "Common features of mineral metabolism markers in TIOs include persistent hypophosphatemia, low 1,25-dihydroxyvitamin D (1,25(OH)2D) levels, normal Ca and 25-hydroxyvitamin D (25(OH)D) levels, and parathyroid hormone (PTH) levels." (PMID 41227266, 2025). "Biochemical analysis showed persistent hypophosphatemia, inappropriately normal 1,25(OH)2D level, and normal levels of parathyroid hormone, calcium, and 25-hydroxyvitamin D. Renal function was normal." (PMID 40980824, 2025). "In the most recent follow-up, the patient had a calcium level of 2.79 mmol/l, hypophosphatemia (0.77 mmol/l), elevated parathyroid hormone level (87.9 pg/mL), and normal urine excretion of calcium and phosphate." (PMID 40357201, 2025). "Laboratory analysis showed hypophosphatemia, normocalcemia, increased alkaline phosphatase activity, and normal serum PTH." (PMID 38355430, 2024). "The mean increase in parathyroid hormone (PTH) from baseline was 50 pg/mLand severe iron deficiency, indicated by low ferritin levels, was the only significantpredictor of persistent hypophosphatemia, apart from baseline phosphate." (PMID 38746050, 2024). "Biochemical parameters demonstrated hypophosphatemia, hyperphosphaturia, slight increase in parathyroid hormone (PTH), high levels of alkaline phosphatase, and elevated FGF23." (PMID 39416269, 2024). "The study also identified hypophosphatemia and hyperphosphaturia in 26% of patients, a reduction in serum calcium in 84%, and elevated parathyroid hormone (PTH) levels in 42% of patients." (PMID 39589949, 2024). "When VDR−/− mice mature on a control diet, they develop rickets because of hypophosphatemia, hypocalcemia, elevated plasma 1,25(OH)2D3 and PTH levels." (PMID 39043847, 2024). "The increased parathyroid hormone (PTH) continues the vicious cycle of hypophosphatemia with prolonged elevation of PTH even after iFGF23 normalizes." (PMID 39408317, 2024). "This variant was initially reported in a patient with high bone mass, unclosed cranial suture, persistent hypophosphatemia, and elevated parathyroid hormone (PTH) levels." (PMID 39285472, 2024). "Decreased calcium levels are a trigger to increase the secretion of parathyroid hormone (PTH), which subsequently induces hypophosphatemia." (PMID 37342302, 2023). "PTH also provides phosphate excretion from the kidneys, or hypophosphatemia, and increases ALP activity." (PMID 38813002, 2023). "When circulating calcium decreases, the body mobilizes calcium underneath the bone, stimulating PTH to maintain adequate serum calcium; in addition, serum calcium levels can also be affected by hypophosphatemia." (PMID 37630705, 2023). "After the patient was delivered to us, we found the patient had hypophosphatemia with normal serum calcium, PTH and creatinine level." (PMID 37417620, 2023). "Bisphosphonates, in addition to being a possible cause of Fanconi syndrome, lead to a decrease in calcium levels, which then stimulates parathyroid hormone (PTH) release, predisposing the patient to significant hypophosphatemia." (PMID 37342302, 2023). "Meanwhile, his laboratory data showed normal serum alkaline phosphatase (ALP) of 41 U/L (normal: 40–150), calcium 2.16 mmol/L (2.15–2.55), parathyroid hormone (PTH) 6.6 pmol/L (1.6–7.9) but mild hypophosphatemia of 0.72 mmol/L (0.81–1.45)." (PMID 37175022, 2023). "At 12 weeks, Dmp1KO mice showed increased serum FGF23 and parathyroid hormone levels, hypophosphatemia, impaired growth, rickets, and osteomalacia." (PMID 37943605, 2023).
hypophosphatemia (continued). "Hypophosphatemia was observed in a significant proportion of patients with Bartter and Gitelman syndrome and appeared to be primarily related to a PTH-independent renal phosphate leak." (PMID 35137195, 2022). "Laboratory tests revealed hypophosphatemia with normal parathyroid hormone (PTH) levels, normal serum calcium, high 24-hour urine calcium, normal 1,25-dihydroxyvitaminD levels, low renal threshold phosphate concentration (TmPO4/GFR), and high FGF23." (PMID 35145798, 2022). "In patients with Gitelman syndrome, high PTH levels have only been described in patients that had parathyroid adenoma, while hypophosphatemia has been reported in several small studies and has been attributed to renal phosphate wasting." (PMID 35137195, 2022). "On the other hand, hypophosphatemia and low serum PTH levels induce 1-α-hydroxylation in the kidney, increasing 1,25(OH)2D3 synthesis, which subsequently increases Pi intestinal absorption and renal Pi reabsorption." (PMID 34068220, 2021). "Because hypophosphatemia is the common denominator of all forms of rickets, the management of the VDDR aims to maintain Ca serum levels in mid-normal range, ensuring a normal serum level of PTH and, consequently a correction of hypophosphatemia." (PMID 34199067, 2021). "Among bone metabolic disturbances, ALP elevation was detected for the first time in 1996, and since then other new cases with hypophosphatemia, low serum calcium and 1,25-dihydroxycholecalciferol and PTH elevation have been identified." (PMID 34360805, 2021). "During the experiment, PTH levels remained low, and the hypophosphatemia was reproduced by injection of FGF23 in parathyroidectomized rats." (PMID 33191899, 2021). "Laboratory tests showed hypophosphatemia, elevated alkalinephosphatase, normal calcium, mildly elevated PTH and normal levels of 25(OH)Dand 1.25(OH)D." (PMID 32897287, 2021). "Six out of nine had mild hypophosphatemia whereas only two had markedly increased PTH; the other biochemical values in these two individuals were normal." (PMID 34258505, 2021). "Parathyroid hormone (PTH) and hypophosphatemia stimulate 25(OH)D-1-α hydroxylase (CYP27B1) activity." (PMID 33659946, 2020). "The link between fair kidney responsiveness and favorable outcomes is compatible with a report that severe hypophosphatemia (defined as phosphate levels < 1.55 mg/dL) within 1 year after KTx (usually a period of high PTH) predicts favorable graft survival." (PMID 32792668, 2020). "Laboratory analysis revealed hypophosphatemia and elevated alkaline phosphatase, parathyroid hormone, and FGF-23." (PMID 31963334, 2020). "The study of calcium-phosphate metabolism was routinely performed during the follow-up according to clinical judgment in three cases (cases I, II, V) and revealed persistent normo-calcemic hypophosphatemia associated with high levels of ALP and PTH." (PMID 32299476, 2020). "Subjects with calciopenic rickets will have elevated serum levels of PTH, which depress the TRP and cause hypophosphatemia." (PMID 32596195, 2020). "She had concomitant hypophosphatemia to 2.6 mg/dL with a normal serum PTH of 48 pg/mL (range 11 to 51 pg/mL)." (PMID 31687646, 2019). "Hypophosphatemia, the most common biochemical alteration associated with MBD of prematurity, causes reduced PTH release which increases renal tubular phosphate reabsorption." (PMID 31032241, 2019). "The highest level of the parathyroid hormone (PTH) and the highest prevalence of hypophosphatemia and osteopenia were demonstrated in VitDd group compared to VitDi and VitDn." (PMID 30211230, 2018). "Another risk is unsustained parathyroid hormone (PTH) suppression and related hypophosphatemia and poor healing of the skeletal findings." (PMID 27796266, 2017). "The disease is characterized by hypophosphatemia and elevated serum PTH levels, with inappropriate renal phosphate wasting." (PMID 29280738, 2017).
hypophosphatemia (continued). "In cases the hypophosphatemia is severe oral phosphate can be added with close monitoring of the PTH levels and urinary calcium excretion since this will increase urinary calcium excretion which can lead to nephrocalcinosis and nephrolithiasis." (PMID 27709474, 2016). "With progressively increasing PTH concentrations, hypophosphatemia develops, which results in impairment of apoptosis of hypertrophic chondrocytes at the growth plate and mineralization of matrix vesicles in the osteoid." (PMID 26800885, 2016). "Patients with severe hypophosphatemia with normal calcium and high PTH have been reported in two cases in our previous study." (PMID 26132292, 2015). "Our experiments also show SPR4-peptide infusion induces changes in Wild type mice that mimic aspects of the HYP mice phenotype (suppressed FGF23, PTH with hypophosphatemia)." (PMID 24839967, 2014). "In this study of 106 prevalent and clinically stable transplant patients with CKD stages 1T to 4T, between 6 months and five years from transplant, we found a high prevalence of abnormalities in mineral metabolism, with hypophosphatemia and PTH elevation." (PMID 22811905, 2012). "PTH also enhances urinary phosphate excretion and contributes to the development of hypophosphatemia." (PMID 20062590, 2009). "In some patients following transplantation, persistent hypophosphatemia is noted, despite relatively modest increases in concentrations of circulating parathyroid hormone." (PMID 18288501, 2008). "Further investigations revealed elevated PTH levels and worsening hypophosphatemia." (PMID 40801029, 2025). "At baseline, the patient demonstrated persistent hypophosphatemia (2.8 mg/dL; reference 2.5–5.5 mg/dL) with normal calcium, elevated alkaline phosphatase (137 U/L; 38–126 U/L), and increased parathyroid hormone (97.1 pg/mL; 18.5–88 pg/mL), consistent with secondary hyperparathyroidism." (PMID 41226894, 2025). "In addition to the preoperative steps, the behavior of FGF23 and PTH induced an increase in phosphaturia and consequent hypophosphatemia." (PMID 39462348, 2024). "Hypophosphatemia in VDDR1A results from elevated PTH and renal phosphate excretion." (PMID 39452491, 2024). "Moreover, PTH levels were significantly elevated in those with phosphate wasting, and this elevation persisted even among individuals with hypophosphatemia." (PMID 37985930, 2024). "PTH is a marker of secondary hyperparathyroidism and, in combination with tubular reabsorption of phosphorus (TRP), can help to distinguish the causes of hypophosphatemia." (PMID 37630705, 2023). "Then, parathyroid hormone (PTH) and creatinine in serum were tested due to hypophosphatemia." (PMID 37417620, 2023). "Due to the phosphaturic effects of PTH, this mechanism may prolong hypophosphatemia after FGF23 returns to normal levels." (PMID 35790696, 2022). "- FGF-23 levels decreased by 97% at 4 weeks after transplant but were still above normal. - FGF-23 levels, but not PTH levels, were independently associated with post-transplant hypophosphatemia." (PMID 35602513, 2022). "Moreover, hypophosphatemia is a frequent feature in pHPT, as PTH inhibits phosphate reabsorption by proximal tubules." (PMID 34768698, 2021). "Blood workup showed hypophosphatemia (2.4 mg/dL), elevated alkaline phosphatase (495U/L), normal calcemia, mildly elevated PTH (97.2 pg/mL; RR <68.3), and normallevels of 25-(OH)-vitamin D and 1.25-(OH)-vitamin D. The radiological evaluationshowed bone deformities of the radius and femur." (PMID 32897287, 2021). "A non-phosphorylated DMP1 could produce a non-functional protein or undergo a faster degradation, leading to hypophosphatemia, calcium binding alterations and increased PTH." (PMID 34360805, 2021). "Secondary elevation of PTH will occur to maintain normocalcaemia, whereas this compensation does not tend to occur with hypophosphatemia and is associated with decreased phosphaturia." (PMID 33614549, 2021).
hypophosphatemia (continued). "A single daily dose of loop diuretics (LDs) could increase renal calcium excretion and alter the diurnal rhythm of plasma parathyroid hormone (PTH) levels, and consecutive doses may ultimately result in elevation of circulating PTH and hypophosphatemia." (PMID 34001070, 2021). "On the other hand, individuals with ADHR have normal PTH with a trend toward high levels, which could be explained by the low 25-hydroxyvitamin exacerbating hypophosphatemia and PTH production." (PMID 34360805, 2021). "In RS, hypophosphatemia and hyperphosphaturia, high PTH and 1,25(OH)2D3 levels occasionally reported could be associated with FGF23 elevation." (PMID 34360805, 2021). "Moreover, hypophosphatemia at 10 weeks of age can be explained by enhanced phosphaturic action due to elevated plasma PTH levels." (PMID 32617522, 2020). "Subjects who have hypophosphatemia and normal serum levels of PTH, calcium, and 25(OH)D are likely to have phosphopenic rickets; a normal or elevated tubular reabsorption of phosphorus (TRP) will be found in subjects with inadequate intake or absorption of phosphorus." (PMID 32596195, 2020). "High PTH levels indicates not only a secondary hyperparathyroidism but, in association with the kidney tubular reabsorption of phosphate (TRP), can discriminate the underlying cause of hypophosphatemia." (PMID 31032241, 2019). "The hypophosphatemia in VDDR1A is a result of elevated PTH and renal excretion of phosphate." (PMID 30282619, 2019). "Also, Coburn and Massry, (1970) have suggested that hypophosphatemia can alter renal handling of Ca and reduces the responsiveness to PTH." (PMID 30609750, 2019). "Laboratory findings showed hypophosphatemia and elevated levels of parathyroid hormone (PTH)." (PMID 31423395, 2019). "The hypothesis provides a mechanism for high [PTH] in response to high IP despite persistent hypophosphatemia." (PMID 28445401, 2017). "In normal subjects, hypophosphatemia will, through an increase in 1,25(OH)2D, reduce PTH levels." (PMID 26543054, 2016). "PTH levels reached up to 48.6 pg/mL after 1 month, coexisting with hypophosphatemia of 2.7 mg/dL." (PMID 26640724, 2015). "Excess of both FGF-23 and PTH have been found to contribute to post-transplant hypophosphatemia." (PMID 24605319, 2014). "The occurrence of hypophosphatemia following kidney transplantation is well described in the literature since during the initial post-transplant period, the accumulated plasma levels of PTH and FGF-23, together with the restored renal excretory capacity, stimulate phosphate excretion." (PMID 38384325, 2024). "A potential unifying hypothesis is that low vitamin D status, especially with low calcium intake, results in a tendency to negative calcium balance and a secondary increase in PTH concentrations, which cause renal phosphate wasting and hypophosphatemia." (PMID 33659951, 2020). "In those patients, hypophosphatemia may be more severe than in the other forms of trauma and yet these patients appear to continue to excrete large quantities of phosphate and have normal serum concentrations of PTH." (PMID 30283881, 2017). "Additionally, hypophosphatemia blunts the production of parathyroid hormone (PTH) and fibroblast growth factor 23 (FGF23), releasing the inhibitory effect of both hormones on renal phosphate cotransporters (NaPi-IIa, NaPi-IIc and PiT-2), thus enhancing renal reabsorption of phosphate." (PMID 28662032, 2017). "However, there is controversy about whether PTH or FGF-23 plays a dominant role in post-transplant hypophosphatemia." (PMID 24605319, 2014). "Laboratory tests revealed hypophosphatemia, elevated alkaline phosphatase (ALP) levels, and increased parathyroid hormone (PTH) levels." (PMID 42221104, 2026). "Among the whole cohort, the only additional patient with hypophosphatemia had normal serum FGF23, αKlotho and PTH levels but hypovitaminosis D (11.8 ng/mL)." (PMID 40133996, 2025).